CD40 (CD40 molecule)
Diseases named in the same sentence as CD40 in open-access papers (continued):
Sharing a sentence is not in itself a finding about the gene and the disease.
pancreatic cancer (95 papers, 2011 to 2025). "has linked the anti-fibrotic potential of anti-CD40 treatment to the recruitment of Ly6Chi monocytes in pancreatic cancer." (PMID 36605208, 2022). "Liver and bile duct cancers, pancreatic cancer, and ovarian cancer most frequently had high CD40 RNA expression (42%, 42%, and 40% of tumors, respectively)." (PMID 41182434, 2025). "For instance, in the phase 2 PRINCE trial for metastatic pancreatic cancer, survival benefit with the CD40 agonist sotigalimab correlated with baseline immune signatures of an active APC compartment and robust CD4 + T cell infiltration." (PMID 41182434, 2025). "Combining a multi-selective RAS(ON) inhibitor with CDK4/6 inhibition and CD40 agonism shifts drug-tolerant persister cells towards senescence and promotes durable tumor regression in pancreatic cancer." (PMID 40299790, 2025). "Specifically, CD40 has been shown to improve the efficacy of checkpoint inhibitors in pancreatic cancer patients." (PMID 38672552, 2024). "Neoadjuvant CD40 agonism in pancreatic cancer resulted in an increased density of DCs and a T cell–enriched tumor microenvironment compared to historical controls treated with chemotherapy, radiation, or no neoadjuvant therapy." (PMID 38181044, 2024). "They identified specific T-cell populations that correlated with improved DFS following anti-CD40 therapy, demonstrating the potential of machine learning in pancreatic cancer immunology research." (PMID 38835055, 2024). "Given the role of artificial intelligence in cancer research, researchers used machine learning to analyze complex tumor molecular data from pancreatic cancer patients and found that anti-CD40 therapy reduced T-cell exhaustion in the TME." (PMID 38835055, 2024). "CD40 agonists were found to alter the pancreatic cancer microenvironment by shifting macrophage phenotype towards M1 and inhibiting human pancreatic cancer in organ section culture." (PMID 39273000, 2024). "Analysis of tumor samples from a clinical trial of another CD40 agonist antibody, selicrelumab, as neoadjuvant therapy in pancreatic cancer demonstrated some notable similarities and differences with our report." (PMID 38181044, 2024). "In a mouse model of pancreatic cancer, the use of a CD40 agonist, FGK.45, induces T-cell infiltration into the tumor." (PMID 37143666, 2023). "A first phase I study with a CD40 agonist monoclonal antibody (CP-870,893) in patients with pancreatic cancer in combination with gemcitabine gave appreciable results." (PMID 37143666, 2023). "Here, we used quantitative immunofluorescence (QIF) to evaluate CD40 expression on the tumor epithelium of solid tumors in large patient cohorts of lung, ovarian, and pancreatic cancers." (PMID 36894898, 2023). "A previous assessment of NSCLC tumor cells expressing CD40 had cited a 51.9% (n = 129) positivity rate, while a previous pancreatic cancer assessment had reported a 69.2% (n = 26) positivity rate." (PMID 36894898, 2023). "For example, preclinical mouse breast and pancreatic cancer models demonstrated that ICI therapy combined with a CD40 agonist increased immune cell infiltration and greater tumor control than ICI therapy alone." (PMID 37928547, 2023). "Preclinical mouse models and pilot human studies involving CD40 agonist antibodies in combination with gemcitabine in the treatment of pancreatic cancer have shown that CD40 activation helps reverse immunosuppression with modest tumor response rates." (PMID 36031601, 2022). "Taken together, these clinical trials shed light on the importance of IL6, TGFβ, CXCR4, and CD40 in cancer treatment, as well as their potential therapeutic effects on pancreatic cancer." (PMID 35453676, 2022). "This can be sustained as a memory T cell response in combination with anti-CD40 repolarisation in a syngeneic pancreatic cancer mouse model, for which anti-CD40 monotherapy is insufficient." (PMID 35020853, 2022).
pancreatic cancer (continued). "Although the benefits of targeting IL6, TGFβ, CXCR4, and CD40 in pancreatic cancer remain elusive, clinical trials for these factors in other cancer types have shown promise." (PMID 35453676, 2022). "A preclinical study has shown the promising efficacy of DC vaccination in combination with CD40-stimulation for pancreatic cancer and deserves future clinical trials." (PMID 35585567, 2022). "In a syngeneic pancreatic cancer mouse model, anti-CD40 mAb treatment resulted in the intra-tumoural migration of hyperinflammatory monocytes and macrophages, which mediated tumour regression." (PMID 35020853, 2022). "LIFE biomaterial was formulated with TiO2 nanoparticles to incorporate anti-CD40 monoclonal antibody in the treatment of mouse pancreatic tumor when average tumor diameter size reached ~4mm." (PMID 36620560, 2022). "For instance, targeting TAM activation using an agonist CD40 antibody was effective against pancreatic carcinoma." (PMID 35837100, 2022). "Recent animal studies have demonstrated promise when combining RT with locally delivered anti-CD40 even for immunologically cold tumors like pancreatic cancer." (PMID 34765538, 2021). "Agonist CD40 antibodies have been developed and tested in clinical trials, in which impressive results have been noted, especially in pancreatic cancer." (PMID 34184409, 2021). "CD40 agonist was also shown to synergize with chemotherapy to induce tumor regression in a genetically engineered mouse model of pancreatic cancer." (PMID 34572013, 2021). "An agonist CD40 antibody was found to modify macrophages to a tumouricidal phenotype in pancreatic cancer." (PMID 34059019, 2021). "Clinical trials using recombinant (s) CD40L or anti-CD40 agonistic antibodies have shown promising results in several malignancies, including pancreatic cancer." (PMID 33180184, 2021). "Systemic administration of Flt3L and agonistic anti-CD40 Ab are also being tested for patients with pancreatic cancer (NCT04536077)." (PMID 34754037, 2021). "Some immunologically cold tumors like prostate and pancreatic cancers show very low expression of CD40 in their microenvironment and foreseeably, very rarely respond to the checkpoint inhibitors." (PMID 34765538, 2021). "Combination of radiation and agonistic anti-CD40 in mouse models of pancreatic cancer also increases T cell priming, as evidenced by the development of local vitiligo from loss of tolerance to melanocyte antigens in the irradiated field." (PMID 34784792, 2021). "To achieve this, we combined a CD40 agonist with interleukin‐15 and tested its potential in pancreatic cancer." (PMID 32821382, 2020). "Agonist anti-CD40 therapy with chemotherapy reversed the complete resistance of murine pancreatic tumors to PD-1 and CTLA-4 blockade." (PMID 32987956, 2020). "In murine pancreatic tumor models, CD40 agonists were combined with anti-PD-1 and chemotherapy to trigger effective T cell immunity." (PMID 32793228, 2020). "CP-870,893, CD40 agonist antibody, induced antitumor activity for breast cancer in vivo and is currently in phase I study in patients with pancreatic cancer and three other phase I trials in patients with advanced solid tumors." (PMID 32947901, 2020). "Although agonist CD40 Abs have been tested for their clinical efficacy as single agent and in combination with chemotherapy in several clinical indications, including pancreatic cancer, evidence for a therapeutic window is still lacking." (PMID 32358491, 2020). "Our findings argue for exploring the therapeutic index of the MEKi/CD40 Ab combination in mutant KRAS-driven tumors such as pancreatic cancer." (PMID 32358491, 2020). "This preclinical data lead to the clinical trial of human CD40 agonist with gemcitabine in advanced pancreatic cancer patients which showed partial responses." (PMID 30853982, 2019).
pancreatic cancer (continued). "Moreover, CD40 protein expression appears to be correlated with lymph node infiltration in lung adenocarcinomas, human esophageal squamous cell carcinoma, gastric cancer and pancreatic cancer, where it was also associated with the clinical stage of the disease." (PMID 31137630, 2019). "Another approach to targeting TAMs has been provided by administration of agonistic anti-CD40 antibody in mice with pancreatic cancer." (PMID 31331034, 2019). "Another example of macrophage targeting comes from the administration of the anti-CD40 antibody in a preclinical model of pancreatic cancer." (PMID 30853982, 2019). "Translation of the results obtained into clinical trials using a fully humanized antibody CD40 agonist in combination with chemotherapy in patients with advanced stage pancreatic cancer achieved partial response and improved patient survival." (PMID 31331034, 2019). "TGFβ blockade, for example, although strikingly effective in combination with radiation in breast cancer, had negligible effect in our KPC pancreatic tumor model, and in fact, reversed the efficacy of anti-CD40." (PMID 30245691, 2018). "Agonistic antibodies to CD40 have been successful in generating limited responses in both mice and humans with pancreatic tumors, in some cases via enhanced T cell priming, and in other cases through activation of myeloid cells." (PMID 30245691, 2018). "Four of the 22 enrolled patients experienced a partial response, which demonstrated the potential of CD40 agonists as a treatment modality in pancreas cancer." (PMID 29891787, 2018). "The first study to investigate the co-stimulatory agonists in pancreatic cancer used CD40 agonist in combination with gemcitabine in 21 patients with locally advanced or metastatic disease." (PMID 26981244, 2016). "CD40 agonistic antibodies (αCD40) in combination with gemcitabine have been reported to show early signs of clinical activity in pancreatic cancer patients." (PMID 26918344, 2016). "Treatment with a CD40 agonist antibody drove the formation of a dense capsule rich in cytotoxic T cells and macrophages that separated the pancreatic tumour from the normal pancreas." (PMID 26918344, 2016). "The use of shrCD40L on pancreatic cancer cell lines significantly inhibited their proliferation and enhanced apoptosis, although the effect was most pronounced in the cells showing high CD40 expression." (PMID 25117071, 2014). "In a recent study, re-educated CD40-activated macrophages rapidly infiltrated tumors and became tumoricidal in pancreas carcinoma." (PMID 24489836, 2014). "The goal of this study is to leverage an immune response resulting from the treatment combination of flash radiotherapy (Flash-RT) and LIFE (liquid immunogenic fiducial eluter) biomaterial incorporating an anti-mouse CD40 monoclonal antibody to enhance the therapeutic ratio in pancreatic cancer." (PMID 41155910, 2025). "CD40 is being investigated as a promising therapeutic target for pancreatic cancer." (PMID 40003965, 2025). "T-cell infiltrations in the pancreatic tumors treated with LIFE Biomaterial_anti-CD40 alone or combined with CONV_5 Gy, CONV_10 Gy, CONV_20 Gy, or Flash_5 Gy alone, respectively, have shown higher permeations of CD11b or CD3, CD4, and CD8 T-cells in the tumor microenvironment." (PMID 41155910, 2025). "Ovarian and pancreatic cancers had the highest proportions of patients exhibiting both high CD40 and low-moderate CD40L expression—33% (14/43) and 24% (13/55), respectively—representing the only two malignancies in which more than 20% of patients had this expression profile." (PMID 41182434, 2025). "Notably, in the context of pancreatic cancer, agonistic anti-CD40 antibody has been reported to activate macrophages that enter the TME, remodel the stroma, and enhance the responsiveness of tumors to chemotherapy." (PMID 38684596, 2024).
pancreatic cancer (continued). "Additionally, the pancreatic adenocarcinoma cohort only allowed for assessment of a single histological type, which prevented a comparison of CD40 expression between different subtypes of pancreatic cancer." (PMID 36894898, 2023). "In contrast, although intraperitoneal administration of FLT3L and CD40 agonist extended survival in mice bearing orthotopic pancreatic cancer compared with ablation monotherapy, the survival benefit from local administration of the hydrogel microsphere vaccine was significantly superior." (PMID 37433774, 2023). "Rejection of subcutaneous tumors and control of a subset of orthotopic pancreatic tumors was correlated to the degree of tumor-specific T cell expansion following implantation and providing DC maturation signals via CD40 at the time of tumor implantation prevented orthotopic pancreatic tumor growth." (PMID 37072485, 2023). "Preclinical studies in subcutaneous and metastatic pancreatic cancer mouse models demonstrated that the combination of a T-cell vaccine, a PD-1 antagonist and a CD40 agonist mAb was able to eradicate most tumours, favouring antitumour immunity by reprogramming immune resistant tumours." (PMID 33917882, 2021). "Moreover, we found that the combination of gemcitabine and nab-paclitaxel, a standard-of-care regimen for pancreatic cancer that has been combined with anti-CD40 in patients, also produced toxicity when administered at 2 days after anti-CD40 treatment." (PMID 34101617, 2021). "Moreover, an agonistic CD40 monoclonal antibody (CP-870,893) in combination with gemcitabine showed partial clinical effects in advanced pancreatic cancer patients." (PMID 34059019, 2021). "Notably, agonistic antibodies to CD40 have shown efficacy in early-stage trials of pancreatic cancer, in part via their ability to mobilize dendritic cells to present tumour antigens and prime naive T cells." (PMID 34784792, 2021). "Likewise, CD40 agonist therapy reprograms the tumor microenvironment and sensitizes the tumor to checkpoint blockade treatment in breast and pancreatic cancers, and osteosarcoma." (PMID 34103524, 2021). "Through reprograming M2-TAMs toward into M1-TAMs, humanized anti-CD40 antibodies could suppress progression of pancreatic cancer and provide a better prognosis, which was confirmed in mouse models and patients with pancreatic ductal adenocarcinoma." (PMID 34026635, 2021). "Interestingly, we observed in 50% of tumor samples of patients with colorectal, bile duct and pancreatic carcinoma a strong expression of CD40." (PMID 33180184, 2021). "Notably, in a second set of experiments, mice spontaneously developing pancreatic tumors treated with the anti-CD40 mAb FGK45 and gemcitabine showed a major tumor regression compared to gemcitabine alone, supporting that observed in the previous model." (PMID 35582441, 2020). "Based on this preclinical evidence, the combination of the APX005M CD40 agonist with Nivolumab plus standard gemcitabine and nab-paclitaxel is currently being tested with promising antitumor activity in pancreatic cancer, where ICIs have been ineffective as single agents." (PMID 32793228, 2020). "Macrophages are also important producers of matrix metalloproteinases (MMPs) and the administration of a CD40 agonist to pancreatic tumour bearing mice stimulated the systemic release of IFNγ and CCL2, thereby promoting the infiltration of MMP13 expressing monocytes/macrophages." (PMID 31331034, 2019). "Building on pre-clinical and early clinical data for simultaneous targeting of CD40 and PD-1 / PD-L1 in pancreatic cancer (a disease for which all immunotherapeutic efforts have failed so far), a phase I trial investigating the combination of CD40, durvalumab and chemotherapy was initiated." (PMID 31217020, 2019).
pancreatic cancer (continued). "We selected anti-CD40 as a rational choice for combination with SBRT in the setting of pancreatic cancer due to previous activity of this agent in mouse models and human pancreatic cancer patients and the potential for augmentation of T cell priming in combination with radiation." (PMID 30245691, 2018). "Anti-CD40 antibody, for example, has been shown to re-activate macrophages in pancreatic cancer mouse models, leading to the recruitment of anti-tumor M1 macrophages to the tumor site, depletion of tumor stroma and consequently to increased efficacy of chemotherapeutic agents such as gemcitabine." (PMID 28750018, 2017). "Accordingly, CD40 represents a promising target in pancreatic cancer." (PMID 26981244, 2016). "The assessment of CD40 expression on the surface of pancreatic cancer cells revealed that at stage I of the disease, the cells were CD40-negative, whereas in patients with lymph node involvement and distant metastases, the cells exhibited high expression of CD40." (PMID 25117071, 2014). "Thus, larger randomized controlled trials will be needed before the role of a CD40 agonist monoclonal antibody in pancreatic cancer treatment can be clearly determined." (PMID 24592240, 2014). "Because CD40 activation can reverse immune suppression and drive anti-tumor T cell responses, the combination of an agonist CD40 antibody with gemcitabine chemotherapy was tested in a small cohort of patients with advanded pancreatic cancer." (PMID 23641216, 2013). "In addition, epigenetic alterations of miRNA-regulated CD40 expression lead to downregulation of CD40 expression in pancreatic cancer cells promoting invasion and metastasis." (PMID 23125850, 2012). "A recent study revealed that activation of macrophages by the infusion of antibodies against CD40 may induce macrophage-mediated tumour regression in 30% of cases in both a mouse model for pancreatic cancer and in patients with pancreatic cancer." (PMID 22778767, 2012). "The exact mechanism of CD40-CD40L interaction is still unclear as CD40 expression has been correlated with worse tumour prognosis, TNM stage, and lymph node metastases, perhaps because the CD40L is rarely expressed on pancreatic cancer TILs and hence unable to downregulate CD40+ cancer growth." (PMID 23125850, 2012). "A recent study revealed that activation of macrophages by the infusion of antibodies against CD40 may induce macrophage-mediated tumor regression in 30% of cases in both a mouse model for pancreatic cancer and in patients with pancreatic cancer." (PMID 22176642, 2011). "Notably, this biologically plausible pattern was detected in 33% of ovarian cancers and 24% of pancreatic cancers, indicating that these tumors may be especially amenable to exogenous CD40 stimulation." (PMID 41182434, 2025). "In addition, the targeting of CD40 with agonistic monoclonal antibodies (mAb) has shown effective results in different cancer types, such as pancreatic cancer, where both the adaptive and innate immune systems drive the main mechanisms of action of the CD40-targeted therapy." (PMID 40578365, 2025). "In addition to TAM depletion, skewing TAMs toward an immunostimulatory M1 phenotype using CD40 mAb may even hold more clinical potential, as CD40 mAb-activated macrophages in pancreatic cancer infiltrate the tumor and facilitate tumor stroma depletion." (PMID 31020037, 2019). "Flow cytometry analysis of mCherry-sorted cells confirmed the successful anchoring of anti-CD40 scFv (αCD40 scFv) and anti-CLDN18.2 (αCLDN18.2 scFv) into KPC pancreatic cancer cells, respectively (left)." (PMID 38468289, 2024). "To align our research with clinical relevance, we thus selected anti-CD40 scFv and anti-CLDN18.2 scFv sequences that enable recognize macrophages and pancreatic cancer in human." (PMID 38468289, 2024).